IGFBP3 (insulin like growth factor binding protein 3)
Diseases named in the same sentence as IGFBP3 in open-access papers (continued):
Sharing a sentence is not in itself a finding about the gene and the disease.
cancer (continued). "It pointed out that there may be an underlying correlation between the m6A modification and BMP1 expression in various cancers, particularly impacting the pullulation and prognosis of those cancers through regulating IGFBP3." (PMID 36267461, 2022). "Evidence shows that some energy homeostasis genes may also regulate signaling pathways involved in cancer development, supporting their potential to modify the association between IGF-1 and IGFBP-3 and the risk of BC." (PMID 35115550, 2022). "Collectively, our results highlight that IGFBP-3 acts as an inhibitor of cancer cell metastasis." (PMID 33801272, 2021). "Other studies found that serum IGFBP3 levels were similar between cancer and control groups, but surgery could reduce serum IGFBP3 levels by decreasing IGFBP3 protease activity." (PMID 34745945, 2021). "Moreover, the potentiation of IGF-1-dependent proliferation by IGFBP3 was documented in fibroblasts, as well as some cancer cells 39,40." (PMID 34512163, 2021). "IGFBP3 has been shown to module radiosensitivity in different types of cancers." (PMID 33712045, 2021). "Our findings reveal the inhibitory effect of IGFBP-3 on cancer migration and metastasis by negatively regulating vimentin expression through ubiquitin-mediated proteasome degradation through the cooperation with the E3 ligase FBXL14 in aerodigestive tract cancer cells." (PMID 33801272, 2021). "According to some studies, high levels of IGF1 in circulation and an elevated IGF1/IGFBP3 ratio disrupt growth hormone (GH)/IGF1 balance, which might be a sign of cancer risk." (PMID 34680577, 2021). "IGFBP-3 has shown antitumor activities by regulating proliferation, migration, adhesion, and/or angiogenesis, and dysregulation of IGFBP-3 has been associated with various human cancers." (PMID 33801272, 2021). "Furthermore, IGFBP-3R has been shown to be responsible for IGFBP-3-induced suppression of NF-κB activity in cancer cells." (PMID 32443727, 2020). "Also, the expression of IGFBP3 and IGFBP7 is frequently reduced in several kinds of cancers, and this decrease is usually caused by promoter methylation." (PMID 32500027, 2020). "Experimental and epidemiologic studies suggest that IGFBP-3 may exert its protective effects by reducing cancer-related mortality." (PMID 32492897, 2020). "Interestingly, previous studies determined that IGFBP3 was a target mRNA of miR-196b, miR-1290, miR-384, miR-34/449 and miR-155 in cancers, but the regulatory mechanism of miR-409-3p/IGFBP3 has not been verified in OS." (PMID 33041662, 2020). "The evidence to this is clear as IGFBP-3 has been demonstrated to be present in high levels in several cancers, including breast, squamous cell lung, clear cell renal and pancreatic cancers." (PMID 32478064, 2020). "In view of the fact that IGFBP-3 generally functions as an anti-proliferative binding protein, increased IGFBP-3 levels may contribute to cancer protection in LS." (PMID 33182502, 2020). "Thus, higher circulating IGFBP-3 would be of great advantage in cancer patients, exerting direct effects on cancer cells as well as reducing IGF bioactivity." (PMID 32056047, 2020). "Furthermore, an increase in IGF1R signaling in response to IGFBP3 downregulation has been indicated as a possible resistance mechanism in cancer treatment." (PMID 33260481, 2020). "Given the fact that IGFBP-3/IGFBP-3R (TMEM219) axis is impaired and shown to have great impact on the survival outcome in specific cancers, IGFBP-3 and TMEM219 may serve as new diagnostic and prognostic biomarkers in specific cancers." (PMID 32443727, 2020). "They demonstrated that 22-mer peptides of IGFBP-3 from the C-terminal domain containing the MBD that functions as a transporter domain could also selectively target the cancer cells." (PMID 32478064, 2020).
cancer (continued). "Low toxicity, specificity of targeting cancer cells for therapy using CPPs from the C-terminal domain of IGFBP-3 could potentially change the treatment regimen for cancer in the future and more research is required in this area." (PMID 32478064, 2020). "Furthermore, serum IGFBP‐3 levels were higher in early cancer stages (I and II) than those of advanced stages (III and IV) (4.78 [3.92, 5.49] vs 3.77 [2.65, 4.59] μg/mL, P < 0.05)." (PMID 31218761, 2019). "IGFBP3 levels have been reported to be correlated with the stage and prognosis of cancer." (PMID 30290787, 2018). "Igfbp3 can function as a pro-apoptotic factor to decrease the survival cancer cells (34, –, 37)." (PMID 29196603, 2018). "This polymorphism (rs2854746) may have an effect on the concentration of circulating IGFBP3, with IGFBP3 levels increasing from CC → GC → GG in cancer-free individuals." (PMID 30643822, 2018). "Interesting, in addition to MTA1, IGFBP3 is also overexpressed in many other human cancers." (PMID 28393842, 2017). "The observed decrease in circulating IGF-1 and IGFBP-3 may contribute to cancer chemopreventive activity." (PMID 28629161, 2017). "To search for IGFBP-3 mediated cancer related activity, we constructed IGFBP-3 siRNA." (PMID 27144338, 2016). "IGFBP3 induced cancer cell proliferation and thus can be used in cancer diagnosis." (PMID 27563882, 2016). "Nuclear IGFBP3 can be observed by immunohistochemistry in cancer and other tissues." (PMID 27563882, 2016). "There is no consistent evidence regarding the association between IGFBP3 level and cancer prognosis." (PMID 27579675, 2016). "Because inhibition of IGF-IR suppresses the adhesion, invasion, and metastasis of various cancer cell types, we reasoned that the inhibitory effect of IGFBP-3 on integrin expression and cell-matrix adhesion may occur through IGF-dependent mechanisms." (PMID 25945837, 2015). "However, increased IGFBP3 has been demonstrated in some other cancers, including renal cell carcinoma, esophageal carcinoma, breast, colon, pancreatic and cervical cancers." (PMID 26540630, 2015). "Another study found that IGFBP-3 arrested the cell cycle at G1/S in several cancer cell lines." (PMID 26670461, 2015). "Functional interaction between EGFR and IGFBP-3 may also promote chemoresistance in TNBC, and delineating the mechanisms involved may identify additional targets for development of therapies in cancers that express both IGFBP-3 and EGFR." (PMID 26221601, 2015). "Insulin-like growth factor binding protein-3 (IGFBP-3) is one of a family of six homologous proteins that bind IGF-1 and IGF-2 with high affinity, and have been implicated as both positive and negative regulators in many cancers." (PMID 26378048, 2015). "The inferior prognosis of CRC patients expressing low IGFBP3 or high levels of IGFBP2 suggests that IGFBPs are also implicated in CRC tumorigenesis, either operating as negative regulators of IGFs activity or exerting IGF-independent effects on cancer growth." (PMID 26528439, 2015). "Furthermore, for IGFBP3 and F3 the procedure is insensitive to the fraction of stromal cells, as long as approximately 2/3 of the tissue material is cancer cells." (PMID 25296164, 2014). "We believe that the effects of fiber intake on IGF system levels and corresponding cancer risk deserve further study.To our knowledge, our study is the first to explore the combined- influence of IGF-1 rs1520220/IGFBP-3 rs2854744 and dietary factors on IGF component levels." (PMID 25285521, 2014). "Studies focusing on the pro-apoptotic and anti-proliferative actions of IGFBP3 have raised hope that these effects could exploited in cancer therapy, but overall conclusions have remained uncertain." (PMID 25374561, 2014).
cancer (continued). "The relationship between circulating IGFBP-3 levels and cancers have been inconsistent." (PMID 25285521, 2014). "Neither IGF-1 nor IGFBP3 was associated with either all cancer death or lung death among men or women in the multivariate analysis." (PMID 23405181, 2013). "Another study showed that IGFBP-3 may play a role in tumorigenesis and that IGFBP-3 levels could be used in future in cancer risk assessment/prevention or as markers of response to cancer treatments." (PMID 23833672, 2013). "IGFBP3 was mainly expressed in the cytoplasm of cancer cells." (PMID 23962053, 2013). "IGFBP-3 alone has been shown to have anti-proliferation effect on numerous cancer cells." (PMID 24143239, 2013). "Despite the small number of cancer cases, there is an epidemiological association of cancer rates in the setting of increased IGF-I levels but not of IGF-binding protein-3 (IGFBP-3), resulting in a high IGF-1 to IGFBP-3 ratio." (PMID 23761782, 2013). "However, IGFBP-3-mediated actions can also occur via activation of a newly discovered cell death receptor, which while capable of activating initiator caspase-8 in cancer cells can also mediate anti-inflammatory effects in healthy endothelial cells." (PMID 22792172, 2012). "Moreover, not only are tissue levels of IGFBP-3 critical but higher circulating IGFBP-3 levels were shown to confer protection from cancer but recently this was brought into question." (PMID 22792172, 2012). "Because of the IGF-I's mitotic properties, lower levels of IGFBP-3, by increasing the IGF-I/IGFBP-3 ratio, may increase the risk of developing cancer, with the opposite occurring when tissue availability of IGF-I is reduced." (PMID 22701472, 2012). "The protective effects of IGFBP-3 in primary retinal endothelial cells appear to contrast with reported actions of IGFBP-3 in immortalized cancer cell lines, where it has been well established that IGFBP-3 promotes apoptosis via several IGF-independent mechanisms." (PMID 21850156, 2011). "We speculate that this may be due to IGFBP3 promoter methylation, as previously reported for other cancers." (PMID 20840765, 2010). "The emerging belief that higher levels of IGFBP3 may decrease mammographic density and may decrease the risk of cancer through low IGF1/IGFBP3 ratio must be further substantiated." (PMID 20302654, 2010). "Indeed, the growth inhibitory and pro-apoptotic effects of IGFBP3 are well established in a variety of in vitro and in vivo cancer models." (PMID 19903356, 2009). "In addition, IGFBP3 potentiates the action of paclitaxel and sensitizes cancer cells to the cytotoxic effects of gefitinib and other chemotherapeutic agents." (PMID 19903356, 2009). "Here, we report that GIST882 cells, which have detectable IGFBP3 protein expression, require IGFBP3 for cell viability, confirming the notion that IGFBP3 may facilitate cancer cell proliferation and survival." (PMID 19903356, 2009). "In mammary epithelial cells, the pro-apoptotic effects of IGFBP-3 was limited to cancer cells." (PMID 18498652, 2008). "Besides polymorphic variation in the IGFBP3 gene, another strong predictor of variability in IGFBP-3 levels was the same IGF1 haplotype that was associated, in the same direction, with cancer risk." (PMID 16404426, 2006). "It is difficult to interpret these associations, with either IGFBP-3 levels or cancer risk, as for none of these SNPs is there any evidence to suggest a possible functional role." (PMID 16404426, 2006). "Since a proteasome-dependent degradation of nuclear IGFBP3 has been described in U-2 OS cells, IGFBP3 may therefore be subject to a rapid turn over by proteolysis in the nucleus of cancer cells." (PMID 17049074, 2006).
cancer (continued). "Mean IGF-I and IGFBP-3 levels were similar for former smokers and never smokers, suggesting that these markers of cancer risk normalise following smoking cessation." (PMID 15354219, 2004). "IGF-1 has been shown to act as a potent mitogen, with anti-apoptotic actions, on various cancer cells, whereas IGFBP-3 may have IGF-1-independent pro-apoptotic activity." (PMID 19570255, 2002). "For example, targeting SERPING1 to modulate complement activation could be beneficial in treating autoimmune conditions, while IGFBP3 could be explored as a therapeutic agent in cancer and metabolic disorders due to its regulatory influence on cell growth and survival." (PMID 40377287, 2025). "Notably, some genes were clearly upregulated in cancer samples, as was the case for IGFBP3." (PMID 40647506, 2025). "IGFBP-3 may also be involved in anti-metastatic signaling in cancer." (PMID 37510722, 2023). "In addition, IGFBPs may play synergistic roles in various cancer-related pathways because a significant correlation was detected, such as IGFBP3-IGFBP4(r = 0.54), IGFBP4-IGFBP7(r = 0.50) and IGFBP5-IGFBP7(r = 0.49)." (PMID 37088808, 2023). "Interestingly, EGFR overexpression also induces IGFBP-3 in cancer cell lines, supporting the idea that EGFR and the IGF-II autocrine signals might act synergistically in a variety of solid cancers." (PMID 38255147, 2023). "Additionally, IGFBP3 could induce Nur77 to translocate from nucleus to mitochondria and result in an activation of apoptotic cascade in many types of cancers." (PMID 35871161, 2022). "Thus, further studies are required to elucidate whether IGFBP-3 plays a role in DM patients with cancer." (PMID 35356065, 2022). "Thus, low expression of IGFBP3 has been related with cancer development and resistance to radiotherapy and chemotherapy and interestingly alterations in the glycosylation pattern of IGFBP3 can modify several molecular events and intracellular pathways related with tumorigenesis." (PMID 34070747, 2021). "Therefore, it is plausible to say that IGFBP-3 might regulate the motility of cancer cells by interfering with the interaction between vimentin and Akt." (PMID 33801272, 2021). "Moreover, IGFBP-3 is reportedly involved in apoptosis and growth inhibition of cancer cells." (PMID 34723984, 2021). "Taken together, these results suggested that IGFBP-3 internalizes and makes a complex formation with vimentin and FBXL14, thereby causing polyubiquitination and proteasomal degradation of vimentin and suppressing EMT-associated metastatic phenotypes of cancer cells." (PMID 33801272, 2021). "This would pave way into understanding the modus operandi of IGFBP-3 in regulating IGF-independent processes and its pleiotropic ability to bind with potential partners thus regulating several cellular functions implicated in metabolic diseases, including cancer." (PMID 32478064, 2020). "It has been suggested that elevated serum IGFBP3 concentrations might protect against cancer." (PMID 31936274, 2020). "Among six high-affinity IGFBPs, which are IGFBP-1 through 6, IGFBP-3 is the most extensively investigated IGFBP species with respect to its IGF/IGF-I receptor (IGF-IR)-independent biological actions beyond its endocrine/paracrine/autocrine role in modulating IGF action in cancer." (PMID 32443727, 2020). "IGFBP3 may activate different signaling pathways in different cancers." (PMID 29075359, 2017). "However, the effects of IGFBP-3 on cell-matrix adhesion, a critical biophysical parameter that affects cell movement during cancer progression, remain unclear." (PMID 25945837, 2015). "However, the expression of IGFBP-3 in the EAC and its association with the malignancy of the cancer and the expression of estrogen receptors remain unclear." (PMID 22720981, 2012).
cancer (continued). "1,25-dihydroxyvitamin D3 has been shown to increase expression of IGFBP-3 possibly by attaching to the BP-3-vitamin D response element (VDRE) on the IGFBP-3 promoter suggesting that some of the cancer promoting effects of IGF-1 may be modified by vitamin D via changes in IGFBP-3 levels." (PMID 22216097, 2011). "In addition, changes in IGFBP-3 protease activity because of cancer may contribute to alterations in IGF-I and -II, indicating the importance of measuring this parameter in addition to IGFs and IGFBPs when evaluating alterations in IGF-I." (PMID 9662244, 1998). "Cytoskeletal regulators (MYL9, TAGLN) and transcription factors (SNAI2) promote EMT and cancer stemness, while PMEPA1, IL6, IL8, IGFBP3, INHBA, and VEGFA contribute to proliferation, angiogenesis, and immune modulation." (PMID 41009714, 2025). "High-intensity resistance exercise reduces IGFBP-1 and IGFBP-3, which are involved in cancer cell growth, reduces cholesterol, and enhances NKCA, which kills cancer cells." (PMID 39156757, 2024). "Studies have widely reported that KRT4, IGFBP3, MMP10, MMP3, and TGFBI are involved in the pathogenesis of LC and other cancers." (PMID 38302910, 2024). "It was shown earlier that the linear, polyanionic, sulfated GAG heparin, known to possess anti-cancer properties, competes for IGFBP-3-binding to cell surface HSPGs resulting in increased IGFBP-3 accumulation in the media." (PMID 36428962, 2022). "Among these candidate molecular targets, nine were significantly enriched in all three cohorts, and five of them (TP53BP1, RIPK2, EHMT2, IGFBP3, and HMOX1) have been reported to have cancer- and chemoresistance-promoting activities simultaneously." (PMID 35606881, 2022). "In contrast, blocking individual cytokines (IGFBP-3, IGFBP-2, VEGF, PDGF-AA, IL-6 or IL-31) in A549-fibrocyte co-culture CM using neutralizing antibodies decreased ET1 and ETA on cancer cells." (PMID 36241617, 2022). "Above, we studied the value of serum IGFBP3 in the diagnosis and prognosis of EJA, using samples collected from the Cancer Hospital of Shantou University Medical College." (PMID 36409444, 2022). "Based on the close association between the activation of the EMT program and the acquisition of cancer stem cell (CSC) properties, we next examined the effects of IGFBP-3 on the regulation of CSC phenotypes." (PMID 33801272, 2021). "Several previous studies have shown that IGFBP3, SOCS3, and MMP14 are related to radiosensitivity in certain types of cancers, which is consistent with our results that these three genes were highly expressed in radioresistant cells." (PMID 34638754, 2021). "Because cancer cell migration is a typical phenotype of the EMT program, we determined the role of IGFBP-3 in TGF-β-induced migration." (PMID 33801272, 2021). "The involvement of IGFBP1, TIMP1, SPP1, IGFBP3, and STC2 in mediating chemotherapy resistance in various cancers have been extensively studied." (PMID 34737677, 2021). "In the last few years, there has been an increasing number of studies and findings regarding the roles and mechanisms of IGFBP3 and IGFBP7, and their relationships with many kinds of diseases, especially in different cancer types." (PMID 32500027, 2020). "One of the major advantage for IGFBP-3 CPP over others, as demonstrated experimentally, is the ability to specifically target the cancer cells." (PMID 32478064, 2020). "This approach allowed us to understand the effect of IGFBP3 and TMEM219 expression on the level of individual cancers and in specific population subgroups." (PMID 32443727, 2020). "The principal binding protein of IGF-1, IGFBP-3, can reduce IGF-1 bioactivity further inhibiting cancer growth." (PMID 32056047, 2020). "Precise data of co-incubation of the IGF-I/IGFBP3 complex with MMP-7 highlighted that such an experiment restores IGF-I-mediated IGF-IR phosphorylation and, at the same time, activates AKT in cancer cell lines." (PMID 32500027, 2020).